MMP2 (matrix metallopeptidase 2)
Diseases named in the same sentence as MMP2 in open-access papers (continued):
Sharing a sentence is not in itself a finding about the gene and the disease.
cancer (continued). "The upregulation of pro-inflammatory COX-2 expression, MMP-2 and -9 have been reported to be associated with the progression of malignant tumors." (PMID 28286419, 2017). "Recently, the associations between MMP2 polymorphisms with cancers have been extensively explored in published meta-analyses." (PMID 28445160, 2017). "MMP2 is highly expressed in cancer tissues and high expression of active MMP2 is associated with risk of metastasis." (PMID 29156719, 2017). "This phenotype has been previously reported to be mediated through the secretion of active MMP-2 by senescent cancer-associated fibroblasts." (PMID 27907906, 2016). "Quantitative real-time polymerase chain reaction (qRT-PCR) analysis showed that transcription of the cancer-associated matrix metalloprotease 2 (MMP2) and MMP9 decreased after silencing of APPL1 and APPL2." (PMID 26583432, 2016). "Numerous studies have been carried out to look for the possible association between the MMP2 -1306 C>T polymorphism and risk of human cancers (colorectal, breast, gastric, esophageal, prostate, lung, and oral cancer)." (PMID 27051552, 2016). "High levels of MMP-2 are associated with an increased of invasion and metastasis in several types of cancer." (PMID 26942004, 2016). "If the statistical epistasis between PARP1 and MMP2 is related to cancer risk, there must be crosstalk or merging of the two pathways, incorporating disparate cancer traits." (PMID 27588484, 2016). "This is because MMP-2 has been widely implicated in cancer cell invasion and metastasis in a wide array of cancer types, including CRC." (PMID 25605009, 2015). "In cancer pathology, MMP-2 and MMP-9 are mainly implicated in the formation of new blood vessels through angiogenesis." (PMID 26637202, 2015). "Of note, considerable effort has been put into the investigation of MMP2 over the past decade, not only because of its association with cancer progression, but as an attractive target for pharmacological inhibition." (PMID 26307680, 2015). "Elevated expression of MMP-2 in cancer cells has been found to be associated with smaller tumors, while expression of MMP-2 by stromal cells has been associated with increased aggressiveness." (PMID 26286584, 2015). "Matrix metalloproteinase-2 (MMP2) is highly localized to the invadosomes of cancer cells, causing degradation of the extracellular matrix and aiding in the invasion process." (PMID 25965832, 2015). "Enhanced expression of miR-874 led to disappearance of cancer stem phenotype in a CD133-positive population that was associated with reduced MMP-2 and uPA protein levels." (PMID 24670365, 2014). "Taken together, our current results show that NTP effectively decreases cancer cell invasiveness via the MMP-2/-9/uPA system, which is associated with Akt and ERK signalings." (PMID 24667444, 2014). "MMP-2 expression has been associated with the invasiveness of many cancer cell lines and is elevated in high-grade tumors, specifically at the invasive front and in vascular invasion." (PMID 24971065, 2014). "MMP-2 has long been implicated in metastatic transformation in a variety of cancer types including PCa." (PMID 25019290, 2014). "In many cancers, it has been shown that the high levels of matrix metalloproteinase (MMP)-2 and/or MMP-9 are associated with the invasive phenotypes of cancer cells." (PMID 23431332, 2013). "MMP-2 which is a predictor of recurrence and metastasis risk in cancer was also found downregulated in McA-SYYCM cells." (PMID 23622143, 2013). "Due to their ECM-degrading ability and confirmed upregulation in almost all cancer entities, MMP-2 has been linked to invasiveness and dissemination." (PMID 24023566, 2013). "Among all MMPs, MMP9 and MMP2 (gelatinase A and B) are reported to be frequently overexpressed in cancer progression and positively associated with metastases." (PMID 23521716, 2013). "Among them, MMP-2 has been shown to be associated with angiogenesis during cancer development and metastasis." (PMID 23861918, 2013).
cancer (continued). "Four studies evaluated MMP2 (−1306) C/T and its association with cancer metastasis, and only three evaluated the association between MMP7 (−181) A/G and metastasis." (PMID 22348060, 2012). "Inhibition of MMP-2 results in a loss of all differences in variations of invasion between different cancer cell models." (PMID 23098186, 2012). "Increased MMP2 expression in cancer-associated stroma and desmoplasia has been widely demonstrated by other groups." (PMID 22408128, 2012). "Among them, MMP-9 and MMP-2 have been found to be highly associated with metastatic spread by various cancers." (PMID 21909361, 2011). "In particular, MMP-2 degrades components of the basement membrane and is strongly implicated in the invasion and metastasis of malignant tumors." (PMID 20534110, 2010). "It is noteworthy that the pathways regulated by Ato target genes, as well as many of the target genes themselves or their mammalian homologues, such as sens, dap, Traf4, and Mmp2 are implicated in cancer." (PMID 20668662, 2010). "Activated phospho-Akt enhanced expression of MT1-MMP and MMP2 is associated with cancer invasion and metastasis, as well as angiogenesis." (PMID 20650008, 2010). "Of the four known membrane type matrix metalloproteinases, MT1-MMP is most often overexpressed one in cancer and is frequently detected in association with the activated form of MMP2." (PMID 20650008, 2010). "It is noteworthy that MMP2 (gelatinase A) has been implicated in invasion and metastasis in several cancers." (PMID 20003259, 2009). "Increased OPN and VEGF levels, activation of p-c-Met and p-Akt, and enhanced expressions of NF-κB and MMP-9/MMP-2 are associated with cancer cell growth, invasion, and metastasis as well as angiogenesis." (PMID 19796390, 2009). "For example, higher MMP-2/TIMP-2 ratios were associated with recurrences in patients with bladder or uterine cervix cancer." (PMID 16776850, 2006). "The expression of MMP-2 has been strongly associated with the progression of malignancy of several types of carcinoma." (PMID 14520459, 2003). "The expression of matrix metalloproteinases (MMP-2) has been previously linked to invasiveness of carcinoma cells." (PMID 14520459, 2003). "In particular, we found that in the lung a trend toward an increase in VIM, as well as of the CDH5, MCAM, and MMP2 mRNAs associated with the metastasis-derived cancer cell lines, whereas the MMP9 gene seemed to be mainly related to the mesenchymal phenotype of these cells." (PMID 40332096, 2025). "Moreover, treatment with HA extract alone and in combination with L-NAME led to significant downregulation of TNFa, VEGFa, COX-2, and MMP-2, which are key components associated with cancer progression and angiogenesis." (PMID 40179064, 2025). "Additionally, these EVs were associated with increased matrix metalloproteinase-2 (MMP-2) activity, which plays a crucial role in the degradation of the extracellular matrix, facilitating cancer cell invasion." (PMID 40040878, 2025). "Thus, patients’ cancers exhibited high expression levels of PTGS2/ESR2/EGFR/JUN/MMP2 genes’ signatures are associated with poor prognosis." (PMID 39707884, 2024). "Among these, MMP2 and MMP9 are the most significant cancer-associated zinc-dependent endopeptidases involved in the invasion and metastasis of various carcinomas and elevated expression levels of activated MMP2 or MMP9 have been correlated with metastasis in patients with PCa." (PMID 39336161, 2024). "Furthermore, MMP-2 plays an emerging role in the regulation of cancer-associated fibroblast infiltration, potentially participating in immunotherapy response." (PMID 39769454, 2024). "Since the MMP-2 activity of cancer cells is associated with the potential for the invasion and metastasis of cancer cells, inhibition of MMP-2 activity by treatment with AST or ChitoAST nanoparticles may affect the metastasis of B16F10 cells." (PMID 38276606, 2024).
cancer (continued). "Additionally, the expression of MMP2 has been found to be associated with poor prognosis and reduced survival rates in cancer patients." (PMID 38560573, 2024). "Moreover, we detected the expression of CCDC113, MMP2 (associated with migration and invasion of cancer cells), BAX and BCL2 in CCDC113 overexpression cells and control cells." (PMID 39261464, 2024). "To gain insights into the molecular mechanisms underlying elaiophylin’s impact on migration and invasion, we performed western blot analysis to assess the protein expression of MMP-7 and MMP-2, two key matrix metalloproteinases associated with cancer cell migration and invasion." (PMID 37894684, 2023). "However, excessive activation of MMP-2 has been linked to various health problems such as cancer and arthritis, whereby it promotes the growth and spread of tumors and contributes to tissue destruction and joint damage." (PMID 37513440, 2023). "The expression of MMPs transcriptionally regulated by E-cadherin cleavage fragments (MMP-2,9, and 14) or harboring association with reflux-attributed cancer (MMP1) were upregulated by acidified pepsin 24 h following 15 min stimulation; induction was rescued by alginate but not the placebo." (PMID 37175640, 2023). "And, the mechanism of the pro-tumorigenic effect was not directly through effects on cancer cells, but rather the through NET-DNA induced autophagy-dependent activation of pancreatic stellate cells, causing increased MMP-2 and -9 production to promote cancer progression." (PMID 36993957, 2023). "To explore whether MMP2 was involved in the process of CAFs infiltration, we first evaluated the association between MMP2 expression and CAFs infiltration across all types of cancer in TCGA." (PMID 36788565, 2023). "These include older age, presence of cancer and its type, type of bisphosphonate agent and duration of therapy, concomitant osteoporosis or osteopenia with cancer, diabetes, corticosteroid therapy, alcohol and chemotherapeutic agents, and gene polymorphisms including MMP2 and CYP2C8." (PMID 36157219, 2022). "Finally, gelatin zymography indicated how specific variants regulate MMP-2 activity which can be interpreted in the context of invasive potential of cancer." (PMID 33718178, 2021). "In addition, matrix metalloproteinase (MMP), ADAMTS1 and Snail are factors associated with cancer migration and invasion; thus, we analyzed MMP-2, MMP-9, ADAMTS1, and Snail expressions in EGFL6 siRNA treated HCT116 and HT29." (PMID 33726836, 2021). "Therefore, we compared gene expression for cancer-associated fibroblast (CAF) markers including MMP2, MMP9, MMP21, TGFA, CXCL12, ITGA3, FAPα, and IL32 in fibroblasts derived from normal skin and MF tumors." (PMID 33941102, 2021). "Furthermore, integrin β1 and MMP2 are known to be key factors in regulating cancer cell adhesion to ECM, and are therefore highly associated with invasion and metastasis." (PMID 34957091, 2021). "Furthermore, MMP-2 and -9 have been linked with the metastatic and invasive potential of cancer cells." (PMID 33917793, 2021). "Experimental metastasis studies have also shown that the downregulation of MMP9 expression in cancer cells by ribozyme could reduce tumor foci in the lungs of mice, consistent with the results observed in Mmp2- or Mmp9-deficient mice." (PMID 32708426, 2020). "Taken together, we hypothesize that RPE has anti-metastatic activity by suppressing cancer cell migration and invasion, which is associated with lower activity and expression of MMP-2 and -9." (PMID 33158043, 2020). "Mmp2 was upregulated in this pathway and is implicated in cancer cell migration." (PMID 32330152, 2020). "This inference can also be testified by previous research conclusions that MMP2 is associated with the molecular classification of some malignant tumors and has a close relationship with invasiveness, proliferation, lymphatic metastasis, and poor prognosis, and our findings are similar to this." (PMID 33115469, 2020).
cancer (continued). "Besides, it seems likely that cell-impermeable inhibitors of HSP90 activity are able to downregulate cancer stemness-associated extracellular proteinases, such as MMP2 and MMP9, whose expression, secretion, and activity are dependent on extracellular HSP90." (PMID 32268506, 2020). "The 5-azacytidine is an epigenetic drug that inhibits DNA methylation, specifically urokinase-type plasminogen activator (uPA) and matrix metalloproteinase-2 (MMP2) promoter methylation, thus causing cancer growth inhibition and induction of cancer invasiveness, respectively." (PMID 33202711, 2020). "Indeed, in LSCC, the ECM degradation is activated during the progression from early stage to middle stage LSCC, indicating that cancer cells of LSCC can secret ECM degradation-associated protein MMP-2 to promote their invasive ability." (PMID 31217907, 2019). "Epithelial-mesenchymal transition (EMT) is a genetic program aberrantly activated in various cancers that is characterized by the loss of cell-cell adhesion protein E-cadherin and the acquisition of mesenchymal biomarkers such as N-cadherin, Vimentin and mmp2." (PMID 30940151, 2019). "MMP-2 was reported to be closely associated with invasion and metastasis in several cancers." (PMID 30359388, 2018). "MMP-2 (gelatinase A) and -9 (gelatinase B), both of which are cancer-associated, zinc-dependent endopeptidases, have been implicated in playing a significant proteolytic role in cancer invasion and metastasis." (PMID 30359388, 2018). "In addition, FUT175 prevented the migration and invasion of cancer cells caused by IR by downregulating the enzymatic activity of MMP-2/-9." (PMID 30336548, 2018). "Previous studies have shown the association of FoxM1 with VEGF, MMP-9 and MMP-2 in various cancers leading to increased invasiveness and migratory ability of cancer cells causing metastasis, and targeting FoxM1 has been shown to inhibit this phenomena via down-regulation of VEGF, MMP-9 and MMP-2." (PMID 29707121, 2018). "Mmp2, along with Mmp1, are the only genes in the fly genome encoding matrix metalloproteinase and are crucial for extracellular matrix homeostasis during normal development, wound repair, and cancer metastasis." (PMID 29256860, 2017). "In some cancers, MMP2 expression is associated with their capacity for metastasis." (PMID 28129656, 2017). "Since matrix metalloproteinases (MMP) are linked with cancer cell migration and invasion, we performed gelatin zymography to analyze the levels of secreted MMP-2 and MMP-9 following OSU-A9 treatment of BxPC-3 and PANC-1 cells for 24 h and found reduced MMP-2 and MMP-9 proteolytic activity." (PMID 28418923, 2017). "This family, and in particular Mmp-2 and Mmp-9, have been implicated in a variety of cancers." (PMID 26654940, 2016). "Elevated expression of MMP-2 or MMP-9 is associated with human cancer invasion and metastasis." (PMID 26637807, 2016). "Additionally, cancer cells have lesser capability to colonize the lungs of MMP2 or MMP9 deficient mice compared to wild type mice and cancer cell proliferation is decreased in tumors obtained from MMP9 knock-out mice." (PMID 25699257, 2015). "The increased activity of MMP-2 suggests that PAR-2 may be implicated in cancer invasion by the MMP/EGFR/MAPK/ERK1/2 pathway." (PMID 26573921, 2015). "In summary, ARs are associated with local cancer cell infiltration, in which MMP-2 and MMP-9 may play important roles in the HCC microenvironment to increase invasion and metastasis." (PMID 25667651, 2015). "Additionally, down-regulated genes are involved, e.g. MMP2, which is a metalloproteinase implicated in cancer progression and metastasis whose increase in expression is associated with a poor prognosis." (PMID 25077705, 2014).
cancer (continued). "To identify the underlying mechanisms governing the effects of EMMPRIN-2 on cancer cell invasion and metastasis, we examined the expression and secretion of uPA, Cathepsin B and MMP-2 in head and neck cancer cells after exogenously modulating the expression of EMMPRIN-2." (PMID 24705283, 2014). "Indeed, enhanced or unregulated expression of MMP-2 is associated with a poor prognosis in cancer patients." (PMID 25547485, 2014). "Silencing of MMP2 causes cancer cell apoptosis by up-regulating Fas/Fas-L and FADD." (PMID 23936390, 2013). "Furthermore, the well-known cancer-associated genetic factors MMP2 and SOX4 co-emerged in the identified interactions." (PMID 23782521, 2013). "Human chorionic gonadotropin (hCG), a hormone essential for pregnancy, is also ectopically expressed by a variety of cancers and is associated with a poor prognosis, which could induce the synthesis of MMP-2 and/or MMP-9, thereby increasing invasiveness in an MMP-dependent manner." (PMID 36230852, 2022). "Indeed, B7-H3 was implicated in cancer aggressiveness since it was shown to modulate migration, invasion and adhesion to the fibronectin of various cancer cells, including melanoma cells, with the regulation of metastasis-associated proteins MMP-2, TIMP-1, TIMP-2, STAT3 and IL-8." (PMID 34572799, 2021). "Indeed, EV-associated heat shock protein-90 released by cancer cells could induce the expression of MMP-2 which activated plasmin, a protease inducing cancer cell invasion." (PMID 34503252, 2021). "The absence of functional FAK blocked cancer cell migration but this constrain could be released by SCC cells expressing high levels of MMP-2 or by cancer-associated fibroblasts, both of them acting as leader cells that push the immobile collective unit towards the ECM." (PMID 33321813, 2020). "As a consequence, looking at the somatic mutations of its composing genes (of which only Matrix Metallopeptidase 2 - MMP2 - has been reported as harbouring cancer-driving alterations in LUAD36) might reveal novel key components of this pathway leading to metastatic transitions." (PMID 29713020, 2018). "Consequently, the variant genotypes (CT/TT) are expected to produce less MMP-2 antigen, which consequently might be associated with decreased cancer risk or better survival of the patients." (PMID 16940985, 2006). "SIP‐SII, a sulfated Sepiella maindroni ink polysaccharide, inhibited cancer cell invasion and migration by blocking MMP‐2 proteolytic activity." (PMID 41546170, 2026). "Treatment resulted in consistent downregulation of Ran and MMP-2 across cancer types, alongside context-dependent modulation of SCF complex components." (PMID 41749864, 2026). "Prinomastat was tested for treating advanced cancer and oesophagus cancer due to its high affinity for MMP‐2, MMP‐3, MMP‐9, MMP‐13 and MMP‐14." (PMID 41546170, 2026). "Several studies have since looked at the interaction of eHSP90α and MMP-2 in cancer cells by studying higher endogenous levels in aggressive cancer cell lines, exogenous gene expression, or adding recombinant protein to culture medium." (PMID 41597241, 2026). "HSP90α KO cells were crucial in determining the complex interplay between extracellular proteins, leading to the discovery of a unique role for an extracellular serine protease, KLK6, in MMP-2 regulation and cell motility in cancer." (PMID 41597241, 2026). "PDA exposure also induced epithelial–mesenchymal transition (EMT), upregulated cancer stem cell markers (CD44, CD117, CD133, Sox2, Oct4, and Nanog), and elevated expression of metastasis- and chemoresistance-associated molecules (MMP-2, MMP-9, MDR1, and MRP1)." (PMID 41596307, 2026). "Fusion peptides significantly induced apoptosis and reduced survival in EGFR/MMP-2 high cancer cells, while sparing EGFR/MMP-2 low cells in standard tissue culture and 3D-spheroids." (PMID 41920242, 2026).